ANXA10 (annexin A10)
Diseases named in the same sentence as ANXA10 in open-access papers (continued):
Sharing a sentence is not in itself a finding about the gene and the disease.
pancreatitis (1 paper, 2023). Inflammation of the pancreas. "Il33 is expressed during pancreatitis by a small subset (4%) of TFF1/ANXA10+Kras-mutant Gastric module-expressing epithelial cells and is predicted to initiate signaling to Tregs and ILCs (Module T8) by binding with its cognate receptor Il1rl1 and co-receptor Il1rap." (PMID 37167403, 2023).
tumor (36 papers, 2011 to 2024). "ANXA10 downregulation in hepatocellular carcinoma has been associated with poor survival rates, higher early intrahepatic tumor recurrence, higher vascular infiltration and a higher grade." (PMID 36247003, 2022). "Some studies have reported that ANXA10 plays a tumor suppressive role by causing proliferation or apoptosis in GC." (PMID 33177783, 2020). "The associations of Cul4A with the ANXA10 tumor suppressor and regulatory mechanisms were also studied." (PMID 31052599, 2019). "Univariate Cox proportional hazards analysis of progression-free survival showed that ANXA10 and established prognostic factors including tumour stage, histological grade, age, and tumour growth pattern were significant risk factors for progression." (PMID 21979422, 2011). "Metastatic disease was the only clinical variable that was significantly associated with ANXA10 expression in muscle-invasive tumours." (PMID 21979422, 2011). "In addition to ANXA1, the ANXA proteins ANXA2, ANXA9 and ANXA10 are associated with tumour cell adhesion, invasion and metastasis." (PMID 36936694, 2023). "In addition, ANXA10 expression was found upregulated in primary and metastatic melanoma and associated with tumor progression, observations reinforced by its promoting role of cell migration in vitro and metastases in vivo." (PMID 36247003, 2022). "They suggested that ANXA10 expression may be associated with tumor progression by promoting cell-cycle progression in the G1 phase through activation of the ERK/MAPK signaling pathway, leading to decreased expression of cyclin-dependent kinase inhibitors (CDKIs)." (PMID 30744186, 2019). "The neural network classifier showed a good performance and outperformed an immunohistochemistry-based signature comprising ANXA1 (annexin A1) and ANXA10 (annexin A10) in recognizing iCCA precursor lesions and pCCA, both showing high similarity with the tumor." (PMID 39199659, 2024). "The results of TCGA-LIHC data, GSE14520 data and GEPIA2 showed ANXA10 expression to also be meaningfully low in tumor tissues." (PMID 36709331, 2023). "Among these genes, CDC42 and ANXA10 are upregulated in various human cancer cell lines and their expression correlates with tumor stage, lymph node metastasis, and patient survival." (PMID 37833712, 2023). "In extrahepatic cholangiocarcinoma, ANXA10 can induce tumour proliferation, EMT facilitation and tumour metastasis." (PMID 36936694, 2023). "Although previous studies have shown that ANXA10 is expressed at low levels in LIHC tumor tissues, the biological function of ANXA10 in LIHC is still unclear." (PMID 36709331, 2023). "In HNC, ANXA10 upregulation was detected in primary OSCC compared to normal tissue, which was more frequent in advanced cases and associated to tumor size." (PMID 36247003, 2022). "LncRNA DLX6-AS1 acting as a miR-513c sponge was found to promote the tumor malignancy progression of HCC through modulating Cul4A/ANXA10." (PMID 36204642, 2022). "It has been proven that abnormal expression of ANXA10 plays a key role in the generation, progression, and prognosis of tumours, although its functional role remains to be clarified and has not been reported in KIRC." (PMID 39290334, 2022). "In relation to its oncopromoter role, ANXA10 has been proposed as a prognostic biomarker and therapeutic target in many tumor types." (PMID 36247003, 2022). "High DDR1 immunostaining score was significantly associated, on univariate analysis, with male sex, left tumor location, BRAF wild type status, KRAS mutated status, and Annexin A10 negativity." (PMID 35205677, 2022). "In the multivariate analysis adjusting for age, sex, tumor location, tumor grade, hepatitis infection, and disease stage, positive annexin A10 remained an independent predictor of poor OS (hazard ratio 1.572, p = 0.034)." (PMID 35227227, 2022). "The immunohistochemistry study yielded positive annexin A10 staining in the tumor tissues of 61 (33%) patients." (PMID 35227227, 2022).
tumor (continued). "Positive annexin A10 was more frequently observed in grade 1 tumor (61%) relative to grade 2 (31%) and grade 3 (22%) tumor." (PMID 35227227, 2022). "Genes whose upregulation is associated with some cancers (TMEM140, ANXA10, ZNF69, CA9, LOXL2, PAGE3, ELFN1) were also on this list, as was a putative tumor suppressor (DEC1)." (PMID 33601339, 2021). "In early GC tissues, ANXA10 was detected in the nucleus and cytoplasm of tumor cells in both diffuse type GC and intestinal type GC." (PMID 33177783, 2020). "According to these data, ANXA10 functions as a tumor suppressor for as long as the tumor cells express ANXA10." (PMID 33177783, 2020). "We defined immunostaining as positive if 10% of the GC cancer cell nuclei showed any visible signals similar to previous studies that evaluated nuclear expression of ANXA10 in tumor cells." (PMID 33177783, 2020). "Former studies have shown that ANXA10 is closely related to some physiological and pathological processes including tumor progression, cell division, and dedifferentiation." (PMID 31208343, 2019). "The downregulation of ANXA10 correlates with decreased differentiation, invasion, and tumor progression, pointing to a possible tumor suppressor role." (PMID 31052599, 2019). "Low LRP1 immunohistochemical expression in adenocarcinomas was associated with higher age, right-sided tumor, loss of CDX2 expression, Annexin A10 expression, CIMP-H, MSI-H and BRAFV600E mutation." (PMID 29507659, 2018). "We also confirmed by qPCR that a subset of these genes (Anxa10, Ctse, Mmp10, Mmp13, Lcp1) were consistently upregulated in shG9a tumor cells compared to controls." (PMID 30455465, 2018). "Downregulation of annexin A10 leads to dedifferentiation, invasion, and tumour progression, implicating this protein as a tumour suppressor." (PMID 29462943, 2018). "ANXA10 expression was heterogeneous in PDAC tissues, however, in most cases more than 50% of tumor cells presented ANXA10 immunoreactivity." (PMID 28369074, 2017). "Abundant ANXA10 expression was predominantly present in pancreatic ductal epithelial cells of PanINs and IPMNs and tumor cells of PDACs." (PMID 28369074, 2017). "Abundant ANXA10 expression was predominantly present in pancreatic ductal epithelial cells of PanINs, IPMNs, and tumor cells of PDACs." (PMID 28369074, 2017). "Note that ANXA10 expression was predominantly present in epithelial ducts or tumor cells in PanINs, IPMNs and PDACs, in which cases the percentage of ANXA10+ cells was assessed within these cells." (PMID 28369074, 2017). "Human serrated morphology CRCs and mouse Cdx2−/− BrafV600E-mutant tumor epithelium aberrantly expressed a number of gastric epithelial markers, including ANXA10, MUC5AC, and PDX1." (PMID 28072391, 2017). "We observed that in the ANXA10-positive tumours, the cancer cells generally revealed a strong but heterogeneous nuclear staining and medium cytoplasmic staining, similar to the non-muscle-invasive tumours." (PMID 21979422, 2011). "In this patient cohort, 15 of 97 patients (15%) had tumours with low ANXA10 expression, whereas 82 patients (85%) showed high ANXA10 expression." (PMID 21979422, 2011). "Low expression of ANXA10 correlated with shorter progression-free survival in patients with stage Ta and T1 tumours (P<0.00001)." (PMID 21979422, 2011). "Therefore, TISIDB’s “Lymphocyte” module was used to explore the relations between abundance of tumor-infiltrating lymphocytes (TILs) and ANXA10 expression." (PMID 36709331, 2023). "The effect of ANXA10 on lung metastasis of xenograft tumor cells in nude mice was also assessed." (PMID 37666806, 2023). "These outcomes suggest that the tumor suppressor effect of ANXA10 is related to m6A; ANXA10 may regulate HNRNPA2B1, IGF2BP3, METTL3, RBM15, YTHDF1 and YTHDF2 to affect the methylation level of LIHC." (PMID 36709331, 2023).
tumor (continued). "The IHC results proved that ANXA10 protein expression was downregulated in tumor tissues." (PMID 36709331, 2023). "To determine whether the expression of ANXA10 was associated with 20 m6A-related genes, we used the median expression value of ANXA10 to divide 374 TCGA-LIHC tumor patients into high (187 cases) and low (187 cases) expression groups." (PMID 36709331, 2023). "Regarding tumor location, the predictive value of annexin A10 was limited to intrahepatic tumors." (PMID 35227227, 2022). "Nevertheless, these apparently contradictory results may reflect the contribution of additional regulatory mechanisms (e.g., translational or post-translational) leading to the frequent up-regulation of ANXA10 protein in over 60% of tumor samples." (PMID 30744186, 2019). "Immunohistochemical ANXA10 expression was successfully evaluated in 340 of 372 tumor samples." (PMID 30744186, 2019). "In addition, possible correlations between ANXA9 and ANXA10 mRNA expression and the tumor grade were assessed using a homogeneous cohort of 243 HPV-negative HNSCC patients." (PMID 30744186, 2019). "Interestingly, the top up-regulated genes encode proteins involved in tumor progression (Cxcr5 and Aicda), while the top down-regulated genes are strong tumor inhibitors (Anxa10 and Expi)." (PMID 30123421, 2018). "In PDACs, ANXA10 also showed a dominant expression in tumor cells within duct-like structures." (PMID 28369074, 2017). "In PDAC, ANXA10 expression was dominantly present on the membrane and cytoplasm of tumor cells." (PMID 28369074, 2017). "Our results show that in the pathological skeletal remain several well known tumor biomarkers are detected such as annexin A10, BCL-2-like protein, calgizzarin, rho GTPase-activating protein 7, HSP beta-6 protein, transferrin and vimentin compared to the control samples." (PMID 24475253, 2014). "The expression of ANXA10 was also investigated in an additional set of 97 more advanced tumours." (PMID 21979422, 2011). "Furthermore, patients with more advanced tumours and low ANXA10 expression had an unfavourable prognosis (P<0.00001)." (PMID 21979422, 2011). "In addition, we found a highly significant association between tumours with concomitant CIS and low ANXA10 expression (P<0.0001, χ2-test)." (PMID 21979422, 2011). "The ANXA10 gene expression levels in tumours from 150 patients were reported previously." (PMID 21979422, 2011). "We also investigated the prognostic value of ANXA10 in more advanced tumours." (PMID 21979422, 2011). "ANXA10 may act as a possible tumor suppressor role in gastroenteric cancers." (PMID 31208343, 2019). "Interestingly, notwithstanding the data above showing that the ANXA10 protein was strongly expressed in human serrated morphology CRC and mouse Cdx2−/− BrafV600E serrated tumor epithelium, it was still a surprise that Anxa10 was the top activated gene in the Cdx2−/− BrafV600E-mutant epithelium." (PMID 28072391, 2017). "Consequently, we observed that the frequency of tumours with low expression of ANXA10 in the two patient cohorts differed significantly with relatively fewer tumours with low expression in the muscle-invasive patient cohort than expected if the marker was stage dependent." (PMID 21979422, 2011). "Selective expression of MSLN, MUC4, ANXA10, and GPC-1 in the neoplastic tissue compared to non-tumor ductal and acinar tissues (p < 0.001)." (PMID 39062863, 2024). "The exceptions are ANXA5, ANXA6, ANXA10 and ANXA11, which play roles in several tumour types, while other ANXA members promote tumour cell proliferation." (PMID 36936694, 2023). "The activities of CA1, ANXA10, and MUC1 were increased in LPS treated IBD enteroids compared to the LPS treated tumor enteroids, while the activities of BAAT, ACSL5, and ENPP6 were decreased." (PMID 35884586, 2022). "The statistical analysis showed that coexpression of ANXA10 and CD24 was highly correlated with PDAC and high-grade neoplasia lesions." (PMID 28369074, 2017).
tumor (continued). "Double immunostaining of ANXA10 and CD24 showed that there was a large overlap between these two markers in PDAC and high-grade neoplasia lesions." (PMID 28369074, 2017). "Moreover, we validated the differential expression of four model genes (CYS2, F11, ANXA10, and SLC22A1) between normal and tumor tissues in the GSE25097 and TCGA datasets." (PMID 39548390, 2024). "Unlike in these neoplasms, ANXA10 expression confers a better overall prognosis in total GC, whilst the opposite effect among tumors is challenging in examining ANXA10." (PMID 33177783, 2020). "ANXA10 expression was not seen in any of the mucin-rich tumor components, where only Cdx2 inactivation was present and BRAFV600E expression was absent." (PMID 28072391, 2017). "A high expression of ANXA10 in tumours without concomitant CIS compared to tumours with concomitant CIS was also shown at the protein level by western blotting and immunostaining." (PMID 21979422, 2011). "Immunostaining revealed strong but heterogeneous nuclear staining and medium cytoplasmic staining of ANXA10 in tumours without concomitant CIS and weak or no staining in tumours with concomitant CIS and in CIS lesions." (PMID 21979422, 2011). "Thus, the majority of metaplastic (ANXA10-positive) tumor cells also showed high nuclear SREBP2 signals in the vehicle-treated mice, and the cholesterol inhibition treatment significantly decreased the expression of both ANXA10 and SREBP2." (PMID 38092754, 2023). "In univariate analysis, a high DDR1 immunostaining score was significantly associated with male sex (p = 0.0195), left tumor location (p = 0.0114), BRAF wild-type status (p < 0.0001), KRAS mutated status (p = 0.0041), and absence of expression of the serrated markers Annexin A10 (p = 0.0097)." (PMID 35205677, 2022). "The overexpression of annexin A10 protein, BCL-2-like protein, calgizzarin, HSP beta-6, RhoGAP-activating protein 7, transferrin, and vimentin among others referred to healthy samples may indicate the presence of tumor in bones." (PMID 24475253, 2014). "However, ANXA10 mRNA levels did not significantly correlate with the tumor grade (p = 0.605)." (PMID 30744186, 2019). "The predominant presence of ANXA10 in pancreatic ductal cells of PanINs and tumor cells of PDACs while absent in normal pancreatic ducts suggested that ANXA10 may be involved in the early development of PanINs and promoting neoplastic progression of PanINs towards prancreatic adenocarcinoma." (PMID 28369074, 2017). "In a recent study, mesothelin, mucin 4 (MUC4), annexin A10 (ANXA10), and glypican 1 (GPC-1) were observed to be selectively expressed in the tumor when compared to non-neoplastic pancreatic ducts and acini." (PMID 39062863, 2024). "In the present study, we focused on the ANXA10 gene expression and in patient cohort 1, we found a 3.2-fold higher ANXA10 expression in tumours without concomitant CIS compared to tumours with concomitant CIS (P=0.000002, t-test)." (PMID 21979422, 2011). "Because the 395 CRCs were represented as very limited tumor regions in the tissue microarray format, we could not reliably assess relationships of PDX1, CDX2 and ANXA10 staining in these CRCs relative to serrated morphology features." (PMID 28072391, 2017).
cancer (30 papers, 2011 to 2026). A tumor composed of atypical neoplastic, often pleomorphic cells that invade other tissues. "It has been reported that ANXA10 expression is associated with poor prognoses in these carcinomas." (PMID 33177783, 2020). "The downregulation of the tumor suppressor annexin A10 (ANXA10), a member of the calcium dependent lipid binding annexin proteins family, has been observed to be associated with poor prognosis and increased metastasis in various cancers." (PMID 31052599, 2019). "The TIMER tool showed that ANXA10 to be expressed at low levels in 2 cancers, namely, CHOL and LIHC." (PMID 36709331, 2023). "Some of the differentially expressed genes included cancer progression factors, such as Tff1 (trefoil factor 1), Anxa10 (annexin a10), Gnai1 (G protein subunit alpha i1), Areg (amphiregulin), and Mmp7 (matrix metalloproteinase 7)." (PMID 35703180, 2022). "Seven upregulated genes (≥2.0-fold), Ccl24 (4.8-fold), Ccl17 (3.9-fold), S100a8 (2.9-fold), Tarm1 (2.7-fold), Anxa10 (2.4-fold), Ptgs2 (2.0-fold), and Ccl22 (2.0-fold) were detected as inflammatory and cancer-promoting genes." (PMID 34948416, 2021). "Positive ANXA10 expression was observed in a total of 219 (64%) cases, mainly detected in the cytoplasm of cancer cells." (PMID 30744186, 2019). "We further explored the expression of the cancer metastasis suppressor ANXA10 after knocking down Cul4A." (PMID 31052599, 2019). "AnxA10 might be useful to identify adenocarcinomas of unknown primary origin, as AnxA10 expression is commonly found in carcinoma of the upper gastrointestinal tract and the pancreatobiliary system." (PMID 29914106, 2018). "To investigate the expression status of ANXA10 identified as a cancer-related gene by our previous microarray data, we performed quantitative real-time reverse transcription-PCR (qRT-PCR) and immunoblotting analyses using seven OSCC-derived cellular lines and human normal oral keratinocytes (HNOKs)." (PMID 23029062, 2012). "In our study, though the positive rates of ANXA10 in early-stage tumors were significantly low, the positive rates in advanced-tumors were significantly increased; this strongly implies that ANXA10 may play an important role in cancer progression." (PMID 23029062, 2012). "Thus, suppressors of AKR family genes and inducers of ANXA10/ZNF165 may reduce drug resistance of cancer cell lines." (PMID 35974335, 2022). "Suggestive of an anteriorization of epithelial identity is the fact that these cancers often express gastric epithelial markers, including mucin 2 (MUC2), MUC5AC, MUC6 and annexin A10 (ANXA10)." (PMID 31739541, 2019). "Manipulating suppressors and induces of ARK family genes, ANXA10, and ZNF162 may be a way to reduce drug resistance of cancer cell lines." (PMID 35974335, 2022). "We also observed that ANXA10 was not visibly expressed in normal epithelium, while it was variably expressed in the cytoplasm of cancer cells." (PMID 30744186, 2019). "In marked contrast, ANXA10 expression was absent in normal epithelium, but variably detected in the cytoplasm of cancer cells." (PMID 30744186, 2019). "ANXA10 showed rare expression on less than 0.1% cells in cancer adjacent normal tissues, which was considered as negative." (PMID 28369074, 2017). "For example, PLEC, ANXA10, EHF, SLC4A, and CUL4A are expressed at high levels in MDA-MB-231 relative to MCF-7 cells, and MAGED1, SYK, and EPCAM are expressed at higher levels in triple-negative cancer tissues relative to non-invasive control tissues." (PMID 26053433, 2015).